SLIT2 (slit guidance ligand 2)
Diseases named in the same sentence as SLIT2 in open-access papers (continued):
Sharing a sentence is not in itself a finding about the gene and the disease.
tumor (continued). "One study found that Slit2–Robo1 interactions stimulate migration and tube formation in LECs and that transgenic overexpression of Slit2 in a mouse tumor model increases tumor lymphangiogenesis and metastasis." (PMID 36672254, 2023). "Here, we revealed that PDAC tumour cells utilize this mechanism for their colonization and outgrowth in the liver by inducing hepatocytes to secrete SLIT2 from the formation of the PMN to the MMN in liver metastasis." (PMID 36792623, 2023). "Flow cytometry analysis of tumor samples showed that Slit2 treatment significantly enhanced tumor infiltration of CD45+/CD11b+ myeloid cells, in contrast to Robo1KO." (PMID 35838343, 2023). "Slit2 has tumor‐suppressive activity in several human malignancies, however, its role in SCLC biology is undefined." (PMID 35838343, 2023). "We implanted SBC5‐Scr or SBC5‐Robo1KO subcutaneously into the nude mice and treated tumor‐bearing mice with Ad‐Slit2 or Ad‐Null." (PMID 35838343, 2023). "Recently, the role of SLIT2 together with the ROBO1 receptor in tumor growth and metastasis has been explored." (PMID 37059586, 2023). "SLIT2 has crucial roles in organ development, including nervous system development), tumor progression, stem cell regulation, and cell proliferation." (PMID 37958523, 2023). "To elucidate the molecular mechanisms used by the Slit2/Robo1 pathway to regulate tumor growth, we performed RNA sequencing on SBC5‐Robo1 KO and SBC5‐Scr cells." (PMID 35838343, 2023). "Several studies reported tumor‐suppressive functions of Slit2 in breast, colorectal, thyroid, and cervical cancers." (PMID 35838343, 2023). "SLIT2 promotes microglia chemotaxis and polarization toward a pro-tumor phenotype through ROBO1 and ROBO2-mediated activation of the PI3K pathway." (PMID 37700840, 2023). "Mechanistic studies have shown that SLIT2-activated macrophages have high phagocytic capacity, are polarized into an anti-tumor M1 phenotype, and inhibit tumor fibrosis by activating MMP13 secreted by macrophages." (PMID 36591235, 2022). "Tumor cell-derived double-stranded RNA acts as an upstream signal to interact with RNA receptor TLR3 to induce endothelial SLIT2 expression." (PMID 36172371, 2022). "Endothelial-derived SLIT2 protein and its receptor ROBO1 reportedly promote the migration and infiltration of cancer cells into endothelial tissue, whereas endothelial Slit2 knockout can inhibit tumor metastasis." (PMID 36172371, 2022). "It has been reported that ROBO1 plays an important role in cancer invasion, migration, epithelial–mesenchymal transition and tumor-induced angiogenesis through SLIT2/ROBO1 signaling." (PMID 36498797, 2022). "The results indicate that the mean HSCORES of FGF18, IL23A, and LIF in tumor tissues were significantly higher than those in normal tissues (p < 0.05), while the opposite trend was observed for SLIT2." (PMID 34017356, 2021). "have recently shown that the deletion of Slit2 from the endothelium resulted in reduced extravasation of cancer cells and therefore metastasis, whereas Slit2 deletion in the tumor enhanced metastasis significantly." (PMID 34777365, 2021). "Recently, we have shown that recombinant Slit2 enhances the population of M1 macrophages in the tumor stroma, as well as phagocytosis, and subsequently tumor progression to metastasis." (PMID 34777365, 2021). "At the end of the treatment, PBS-treated PyMT mice had a significantly greater tumor volume than Slit2-treated mice as tested by unpaired t-test (*p < 0.005)." (PMID 34777365, 2021). "Slit guidance ligand 2 (Slit2), a tumor suppressor gene, was found to play diverse roles in apoptosis, neurogenesis and angiogenesis of many malignancies by binding to its receptor Robo1 and then transducing the intracellular signaling." (PMID 33621954, 2021). "Fibroblasts in cancer associated status diminish SLIT2 production and subsequently by upregulation of CXCL12 as an agitation signal, promote metastatic behavior of tumor cells." (PMID 32384110, 2020).
tumor (continued). "Although SLIT2-induced tumor suppression has been presumed to be due inhibition of cancer cell migration, its effects on cancer cell growth have not been carefully elucidated." (PMID 32807784, 2020). "For instance, up-regulation of ADIPOQ, AGTR1, AHNAK, ENDRA, RBP7 and SLIT2 was correlated with larger tumour size and more advanced tumour stage." (PMID 33184436, 2020). "Slit2, a secreted protein, interacts with its receptor Robo1 to regulate the differentiation of intestinal stem cells and participate in inflammation and tumor development." (PMID 32398956, 2020). "SLIT2 also inhibits macropinocytosis in RAS-transformed cancer cells, thereby decreasing their survival in nutrient-deficient conditions which resemble tumor microenvironment." (PMID 32807784, 2020). "Further experiments have shown that, in MiaPaCaTR-Slit2, Slit2 can inhibit direct invasion and metastasis of tumor cells." (PMID 32670371, 2020). "In particular, secretion of SLIT2 by tumor cells generates a signaling gradient that attracts ECs as a fundamental step in the generation of a novel vessel network." (PMID 33287867, 2020). "SLIT2 interacts, with its cognate receptor ROBO1 in the human umbilical vein endothelial cells (HUVECs) and tumour-associated endothelial cells." (PMID 33318575, 2020). "In summary, our data highlight the tumor suppressive function of SLIT2 in APL and its deteriorating effects on disease progression when downregulated." (PMID 33120864, 2020). "Further gene ontology and enrichment score analysis associated low SLIT2 expression with cell cycle progression, negative regulation of apoptosis, and DNA replication, reinforcing the notion that SLIT2 acts as a tumor suppressor gene in APL." (PMID 33120864, 2020). "While SLIT2 full-length (FL) is expressed and released by tumor cells, SLIT2-ΔE15 is mainly present in normal tissues." (PMID 33287867, 2020). "Accordingly, Slit2 expression was also increased in tumor tissues at different stages in patients with CRC, as shown through analysis using the MERAV database." (PMID 31242633, 2019). "Slit2 is one of the tumor-suppressive angiocrine factors that is negatively regulated by the EphA2 receptor on ECs." (PMID 31600937, 2019). "The increased Slit2 in the tumor microenvironment was mostly Slit2-WT, which lacks growth inhibitory activity." (PMID 30717252, 2019). "Knock‐down of USP33 in Slit2 expressing GC cells, however, diminished the inhibitory effects of Slit2 on tumour metastasis." (PMID 30896071, 2019). "Slit2 binds to Robo1 in tumor cells, and plays an important role in the regulation of tumorigenesis and metastasis." (PMID 31242633, 2019). "Methylation analysis of the Cdh1, Cdh2, Mmp9, Mki67, Gfap, Gap43, Robo2, and Slit2 genes from tumor samples demonstrated that all of them were methylated in their promoter regions unlike those from normal tissues." (PMID 31921388, 2019). "This study suggests that activation of Slit2/Robo1 signaling in CRC induces tumor metastasis partially through activation of the TGF-β/Smads pathway." (PMID 31242633, 2019). "In contrast, Slit2/Robo1 signaling plays an oncogenic role in tumorigenesis by enhancing tumor growth in intestinal tumors and osteosarcoma." (PMID 30717252, 2019). "The MERAV database, which is a collection of aggregate array data for deeper analysis of gene expression in cancers, is used to analyze Slit2 expression in tumor tissues of CRC." (PMID 31242633, 2019). "Our study clearly showed an increased expression of Slit2 in the tumor tissues and serum of patients with CRC compared with healthy controls through an analysis of the MERAV database and ELISA assay detection." (PMID 31242633, 2019). "The expression of Slit2 was significantly increased in the tumor tissues of CRC patients compared to normal human intestine tissues." (PMID 31242633, 2019).
tumor (continued). "Slit2 binds to Robo1, which is mainly expressed in tumor cells, and its important role in the regulation of tumor growth and metastasis in CRC has been extensively studied." (PMID 31242633, 2019). "During the process of carcinogenesis, there is an inactivation of the Slit2 and Robo2 genes, being therefore considered as tumor suppressor genes." (PMID 31921388, 2019). "Loss-of-function experiments in tumour cells showed that ROBO1 and ROBO3 receptors are involved in pancreatic cancer cell migration and metastasis, and SLIT2 has a role in neural remodelling associated with PDAC11,12." (PMID 30504844, 2018). "A transmembrane receptor of the immunoglobulin family, ROBO1interacts with SLIT2 (Slit Guidance Ligand 2) to regulate many biological functions, is differentially expressed in human cancers, and has a possible role as a tumor suppressor gene." (PMID 29698419, 2018). "MMPs are associated with cancer cell invasion and metastasis.Whereas, slit homolog 2 (SLIT2) is a tumor suppressor gene." (PMID 29187162, 2017). "miR-218 is encoded within intronic sequences of SLIT2 and SLIT3, which act as a tumor suppressor gene in many cancers." (PMID 27285984, 2016). "Altogether, 151 up- and 64 down-regulated genes were identified between UVB-irradiated and non-irradiated skin biopsies, among which down-regulated DNAJB4 and SLIT2 were annotated as tumor-suppressors and up-regulated KIT was annotated as an oncogene." (PMID 27829444, 2016). "Secretion of the highly positively polarized gene SLIT2 from normal epithelial cells has the potential of exerting a tumour suppressor activity as shown by our clonogenic assay on tumour cells exposed to diluted conditioned media." (PMID 27124473, 2016). "Slit2 is frequently downregulated in many types of cancers and exhibits tumor suppressive functions, especially inhibition of tumor cell migration." (PMID 27923383, 2016). "In this study, we confirmed that srGAP1 binds to Robo1 in responding to the Slit2 treatment and mediates its tumor suppressive function in CRC." (PMID 27923383, 2016). "Ectopic expression of Slit2 activated Slit2/Robo1 signaling and promoted tumorigenesis and tumor growth." (PMID 25605242, 2015). "In CRC, Slit2 has been shown to induce apoptosis, inhibit cell migration and thus was believed to be a tumor suppressor." (PMID 25605242, 2015). "The tumor tissues from the ApcMin/+;Slit2 mice showed an increased co-localization of Slit2/Robo1 compared to the tumor tissues derived from the ApcMin/+ mice." (PMID 25605242, 2015). "Further analysis of the tumor tissues from the ApcMin/+;Slit2 mice and DMH/DSS-Slit2 mice revealed that activation of Slit2/Robo1 signaling led to an increased pSrc (Tyr 416) in these tumor tissues compared with their respective controls." (PMID 25605242, 2015). "Co-localization of Slit2/Robo1 was also seen in the tumor tissues from the DMH/DSS induced Slit2-Tg (DMH/DSS-Slit2) mice." (PMID 25605242, 2015). "All these results indicated that tumor cells with low Slit2/Robo1 expression potentially had metastatic intention." (PMID 26400100, 2015). "Their results have showed SLIT2 can attract vascular endothelial cells and promote tumor-induced angiogenesis." (PMID 26674478, 2015). "On the other hand, in many tumors, SLIT2 also has been reported as the putative tumor suppressor being inactivated by promoter hypermethylation." (PMID 24689049, 2014). "According to earlier views ROBO4 inhibits the migration of heterologous cells (that express ROBO4) and primary endothelial cells by interacting with SLIT2, resulting in downmodulation of tumor growth." (PMID 24689049, 2014). "Slit2-induced Robo1 signaling was identified as one mechanism by which CAFs exert a tumor-suppressive effect." (PMID 24734219, 2014).
tumor (continued). "miR-218 has also been shown to affect cancer progression by inhibiting tumor cell migration and metastasis via the repression of the Slit2/Robo1 pathway in gastric and in nasopharyngeal tumors, respectively." (PMID 23226307, 2012). "In total, increased HIC1 and SLIT2 promoter methylation and decreased expression were observed in 70.0% and 51.7% of the tumor samples, respectively." (PMID 22140553, 2011). "SLIT2 also inhibited the invasion of numerous different types of tumour cells including those from the prostate, breast, endometrium and ovary." (PMID 22132142, 2011). "Slit2 has been widely identified in various human cancers, and the interaction between Slit2 and Robo1 is thought to induce tumor angiogenesis." (PMID 21686327, 2011). "Conversely, Slit-2 treatment stimulates endothelial cell migration in vitro and tumor angiogenesis in vivo." (PMID 22194972, 2011). "Decreased miR-218 levels eliminate Robo1 repression, which activates the Slit-Robo1 pathway through the interaction between Robo1 and Slit2, thus triggering tumor metastasis." (PMID 20300657, 2010). "In contrast, SLIT2 also was proposed to be a tumor suppressor gene, which was silenced epigenetically in lung, breast, colon cancers and gliomas." (PMID 19114000, 2008). "We also provide quantitative evidence for potential use of ROBO1, ROBO4 and SLIT2 for prediction of tumor stage and differentiation status." (PMID 19114000, 2008). "In the same study, SLIT2 exhibited overexpression in tumor cell lines and primary tumors of a variety of tissues." (PMID 19114000, 2008). "We also observed that ROBO1 and SLIT2 differentiated histopathological subgroups of liver tissues depending on both tumor staging and differentiation status." (PMID 19114000, 2008). "It was shown by immunohistochemical staining that SLIT2 protein also was present in HCC tumor sections." (PMID 19114000, 2008). "SLIT2 promoter methylation was also detected in one out of 12 of the matching normal kidney tissue samples for methylated tumours." (PMID 14735202, 2004). "In tumours with SLIT2 methylation, CASP8 and RASSF1A were methylated in 43% (six out of 14) and 36% (five out of 14), respectively." (PMID 14735202, 2004). "We have demonstrated that SLIT2 methylation is common in paediatric and adult cancers, and further analysis of additional tumour types seems indicated." (PMID 14735202, 2004). "CASP8 methylation was detected in 36% of SLIT2 methylated and 41% SLIT2 unmethylated tumours (P=1.0)." (PMID 14735202, 2004). "SLIT2 methylation was detected in zero of six normal tissue samples corresponding to the methylated tumours." (PMID 14735202, 2004). "We went on to analyse the ligand SLIT2 located at 4p15.2 for genetic/epigenetic inactivation in tumours." (PMID 15534609, 2004). "The Slit2/Robo signaling pathway acts as a tumor suppressor in various cancers." (PMID 41227302, 2025). "SLIT2 has also been shown to act as a tumor suppressor in a range of cancers including NSCLC." (PMID 38902704, 2024). "Despite the effect of estrogens on tumor growth in cells overexpressing SLIT2, the role of estrogen receptors in this process remains largely unknown." (PMID 39596804, 2024). "Similarly, Robo1Fc, a Slit2 ligand trap protein, was administered to mice to achieve lower Slit2 levels, with vascular dysmorphia and tumor size being significantly reduced." (PMID 39456164, 2024). "Furthermore, ECs downregulate Slit2, a tumor-suppressive angiocrine factor inhibited by EphA2, thereby facilitating tumor proliferation and motility." (PMID 37666809, 2023). "Interestingly, the SBC5‐Robo1 KO tumors treated with Ad‐Slit2 also showed the highest inhibition of tumor growth." (PMID 35838343, 2023). "Multiple microRNAs have been shown to control Slit2 and Robo1 post-transcription in tumor cells." (PMID 37238655, 2023).
tumor (continued). "In our study, we found that aberrantly high SLIT2 expression could participate in the coadaptation of hepatocyte-derived tumour cells and microenvironment cells in liver metastasis progression." (PMID 36792623, 2023). "As SBC5‐Robo1KO tumor growth was inhibited by rSlit2 treatment, we hypothesized that Slit2 may activate host immune cells to restrict tumor growth." (PMID 35838343, 2023). "Furthermore, patient-derived metastatic liver specimens were used for IHC-P staining of P-p38, and the results illustrated that tumour cells with activated P-p38 were surrounded by an abundance of SLIT2." (PMID 36792623, 2023). "In addition to targeting tumor cell proliferation, our results show that Slit2 activates anti‐tumor macrophages, inducing anti‐tumor TME." (PMID 35838343, 2023). "SLIT2 overexpression or the deletion of ROBO1 restricts tumor growth in vitro and in vivo." (PMID 35838343, 2023). "On the other hand, metastatic tumors may induce differential expression of SLIT2, with higher expression in endothelial cells relative to tumor cells." (PMID 36942388, 2023). "SLIT2 - Slit guidance ligand 2 (SLIT2) has been observed to have tumor suppressing activity." (PMID 38304289, 2023). "In addition, tumor endothelial cells can promote tumor progression by down-regulating the expression of tumor suppressor factors, such as Slit2." (PMID 35579998, 2022). "Taken together, these results indicated that ROBO1 may serve as a tumor suppressor in CCA progression, and ROBO1E280* is a loss-of-function mutation, interrupting the SLIT2/ROBO1 signaling pathway and reversing the tumor-suppressing effects of wild-type ROBO1." (PMID 35615148, 2022). "Additionally, we identified a deleterious nonsense mutation, ROBO1E280*, in CCA, which loses the tumor-suppressing function of wild-type ROBO1 due to its translocation and interruption of the SLIT2/ROBO1 signal pathway." (PMID 35615148, 2022). "In contrast, Slit2 knockout in the tumor can promote metastasis." (PMID 36172371, 2022). "Additionally, Slit2 induces tumor angiogenesis via Slit–Robo signaling and Slit2 overexpression in the mouse brain has been reported to increase blood vessel density and permeability." (PMID 35163822, 2022). "Slit2 exerted tumor suppression effects by binding to Robo1 receptor expressed in cancer cells." (PMID 33614646, 2021). "The expression of Slit2 was low in Hela cells, and it was speculated to be an important tumor suppressor." (PMID 33621954, 2021). "The Slit2/Robo1 signaling pathway was reported to participate in the tumor progression of CC." (PMID 33621954, 2021). "Recent studies also highlight the dual nature of Slit2 in cancer suppression or progression based on whether the tumor or surrounding cells produce and secrete this protein." (PMID 34777365, 2021). "This single dose of Slit2 resulted in significant impediment of tumor growth in PyMT mice." (PMID 34777365, 2021). "Therefore, Slit2-induced programming of bone marrow monocytes toward the M1 phenotype and their increased infiltration in tumor stroma potentially result in tumor attenuation." (PMID 34777365, 2021). "Moreover, myeloablated PyMT mice injected with Slit2-treated bone marrow allografts showed a marked reduction in tumor growth, with enhanced recruitment of M1 macrophage in their tumor stroma." (PMID 34777365, 2021). "A recent study has indicated that Slit2 was low expressed in Hela cells, and it might be a vital anti-tumor gene." (PMID 33621954, 2021). "In breast cancer, CAFs derived Slit2 acted as a tumor inhibitor." (PMID 33614646, 2021). "Importantly, downregulated Slit2/Robo1 signaling is reported to suppress the tumor progression by regulating beta-catenin." (PMID 33621954, 2021). "SLIT2 increase is the sign of anti-cancer Characteristics of NAF in the tumor microenvironment." (PMID 32384110, 2020).